EGFR (epidermal growth factor receptor)
Diseases named in the same sentence as EGFR in open-access papers (continued):
Sharing a sentence is not in itself a finding about the gene and the disease.
lung adenocarcinoma (continued). "EGFR and KRAS mutations were detected in 233 (45%) and 56 (11%) of the total 521 lung adenocarcinoma patients, respectively." (PMID 24179496, 2013). "In line with such a concept, EGFR expression was assessed in the present study in the primary lung adenocarcinoma tissues of various -216G/T genotypes by immunohistochemical staining." (PMID 24137392, 2013). "Somatic mutations within the tyrosine kinase (TK) domain of the epidermal growth factor receptor (EGFR) gene are found in approximately 30% of lung adenocarcinomas in Asian populations." (PMID 23419122, 2013). "In the first set of experiments, we utilized PC-9 and HCC827 cells, which are human lung adenocarcinoma cell lines with deletions of exon 19 of EGFR, resulting in activation of this gene." (PMID 24386407, 2013). "EGFR mutations were detected in 10% (7/71) and KRAS mutations were detected in 35% (19/54) of the lung adenocarcinoma cases." (PMID 23817662, 2013). "In contrast, according to a study including EGFR wild-type and advanced-stage lung adenocarcinoma patients who received either monotherapy or platinum-doublet chemotherapy, ALK positivity conferred superior overall survival." (PMID 27234388, 2013). "The mentioned transcription factors show the same expression pattern as that of EGFR in lung adenocarcinoma." (PMID 23874428, 2013). "Several other studies have also indicated a critical role for EGFR overexpression in the metastasis of lung adenocarcinoma." (PMID 24137392, 2013). "Our approach was to delineate mechanisms of constitutive phosphorylation of EGFR in lung adenocarcinoma cell lines." (PMID 23866081, 2013). "Recently, it was reported that miR-145 inhibits cell proliferation of human lung adenocarcinoma by targeting EGFR, indicating that miR-145 is a tumor suppressor miRNA." (PMID 24040120, 2013). "With the increasing application of targeted EGFR tyrosine kinase inhibitor (TKI) therapy in adenocarcinomas of the lung, several resistance mechanisms against this therapy have emerged." (PMID 23536778, 2013). "Somatic mutations in the epidermal growth factor receptor (EGFR) result in enhanced receptor signaling, predicting sensitivity to EGFR tyrosine kinase inhibitors (TKIs), such as erlotinib and gefitinib, in subsets of patients with lung adenocarcinoma." (PMID 24189400, 2013). "NGS technology has also recently shown to be high sensitive in EGFR single gene testing in cytology samples obtained from bronchoalveolar lavage and pleural fluid of lung adenocarcinoma patients." (PMID 24236184, 2013). "Some of the genes such as PIK3CA, TAF15, VAPB, Appl1, Rab5a, ARF4, and XIAP in Merged-module activate the PI3K-Akt pathway and are overexpressed in a manner similar to that of EGFR in lung adenocarcinoma." (PMID 23874428, 2013). "One hundred and ninety-one patients with advanced lung adenocarcinoma, who were resistant from EGFR-TKIs and then received subsequent chemotherapy, were identified." (PMID 24113006, 2013). "These genes include SMARCC1, TRA2B, CBX3 and PRPF6 that show the same upregulation pattern as EGFR in lung adenocarcinoma and we have reported all the mentioned genes for the first time in lung adenocarcinoma." (PMID 23874428, 2013). "In this study, we confirmed that EGFR-TKI had anti-tumor effects in not only lung adenocarcinoma but also tongue squamous cell carcinoma." (PMID 23592411, 2013). "A 48-year-old Caucasian male presented with a Stage IV, TTF1 positive, EGFR wild-type adenocarcinoma of the lung." (PMID 23617826, 2013). "Recent sequencing data shows that RASA1 mutations are observed in lung adenocarcinoma (COSMIC database), so further effort should be directed towards understanding the relationship between RASA1, DOK2, EGFR, and KRAS in lung adenocarcinoma." (PMID 24255704, 2013).
lung adenocarcinoma (continued). "Clearly, further molecular stratification within the EGFR and KRAS mutation-defined lung adenocarcinoma groups has the potential to reveal new targets for synergistic treatment and provide insights into resistance mechanisms." (PMID 24205279, 2013). "Although many promising treatments have been recently developed for adenocarcinoma of the lung, including EGFR-TKI (tyrosine kinase inhibitor) and pemetrexed, there are few optimal treatments that can be used for Sq." (PMID 22788963, 2012). "In lung adenocarcinoma, such driver genes include epidermal growth factor receptor (EGFR), KRAS, BRAF, PIK3CA, and EML4-ALK." (PMID 22768234, 2012). "Previous studies demonstrated that mutations in the KRAS proto-oncogene are responsible for 10–30 % of lung adenocarcinomas, while mutations and amplification of EGFR are common in NSCLC and provide the basis for treatment with EGFR-inhibitors." (PMID 22537942, 2012). "The negative correlations between growth factor signaling and lipid metabolic pathways reported here seem to indicate an inhibitory effect of cholesterol on EGFR pathways in lung adenocarcinoma." (PMID 22211244, 2012). "In lung adenocarcinoma, the increased expression of EGFR protein was found in 19 (40.4 %) tumor cases and, in squamous cell carcinoma, 22 (30.1 %) cases had overexpressed EGFR protein (P = 0.246)." (PMID 22537942, 2012). "This suggests that the young patients with advanced lung adenocarcinoma have a poorer treatment response compared to the general population, especially with regard to EGFR-TKI." (PMID 22695392, 2012). "We present a case of a 77-year-old man with an initial PET-CT scan showing high 18F-FDG intake, suggesting a bilateral pneumonia, who was finally diagnosed of an EGFR-mutant lung adenocarcinoma." (PMID 22957291, 2012). "Epidermal growth factor receptor (EGFR) tyrosine kinase inhibitors are widely used to treat lung adenocarcinomas, especially in non-small cell lung cancer (NSCLC), with EGFR-activating mutations." (PMID 23208557, 2012). "The dual EGFR and Her2 inhibitor BIBW 2992 is currently being tested in a phase 2 and 3 clinical trial to explore efficacy in patients with lung adenocarcinoma harboring wildtype EGFR." (PMID 22363766, 2012). "HGF expression can induce EGFR-TKI resistance to lung adenocarcinoma cells with EGFR-activating mutations, and MET inhibition can reduce proliferation of lung adenocarcinoma cell lines that show resistance to EGFR-TKIs." (PMID 22211244, 2012). "EGFR alterations occur in ∼10% of western and ∼50% of Asian patients with lung adenocarcinoma, a histology which comprises 44% of NSCLC cases." (PMID 22363766, 2012). "We then determined the EGFR status of 213 patients with advanced or metastatic lung adenocarcinomas for selection of to anti EGFR therapies." (PMID 21575212, 2011). "Expression of EGFR and its specific ligands suggests that in human lung adenocarcinoma CALU-3 cells an EGFR-driven autocrine pathway is relevant for cancer cell proliferation." (PMID 21750552, 2011). "Coimmunoprecipitation experiments in these and other lung adenocarcinoma cells confirmed that ERβ and EGFR interact in a gender-dependent manner and in response to E2 or EGF." (PMID 21951318, 2011). "A 73-year-old Japanese man was histologically diagnosed with lung adenocarcinoma harboring an exon 19 deletion in the epidermal growth factor receptor." (PMID 22937431, 2011). "The development of EGFR inhibitors gefitinib and erlotinib initially showed dramatic effects in the treatment of lung adenocarcinoma; however, tumours frequently acquire resistance to the drugs, resulting in treatment failure." (PMID 21285982, 2011). "Due to the potential high benefit of EGFR TKI therapy for treatment of lung adenocarcinomas, several clinically trials have focused on lung adenocarcinomas." (PMID 20637128, 2010).
lung adenocarcinoma (continued). "They assessed EGFR status in a tissue microarray (TMA) of 61 lung adenocarcinomas by IHC, fluorescent in situ hybridization (FISH) and direct sequencing and compared their results with those of conventional methods performed on whole-tissue sections." (PMID 21167064, 2010). "It was demonstrated that mutations in exons 18 to 21 of the tyrosine kinase domain of EGFR were correlated with a high response to EGFR TKIs in lung adenocarcinomas." (PMID 20637128, 2010). "In our study, 68.4% (91/133) of lung adenocarcinomas were EGFR IHC-positive according to our interpreting criteria." (PMID 20637128, 2010). "We determined AI in both wild type and mutant case for KRAS and EGFR genes among the 45 lung adenocarcinomas with SNP data." (PMID 19826477, 2009). "In one EGFR mutant lung adenocarcinoma cell line, R1507 and erlotinib co-treatment induced apoptosis, whereas treatment with either drug alone induced only cell cycle arrest." (PMID 19806209, 2009). "For example, one of the standard second line therapies of lung adenocarcinoma in the U.S. is the use of epidermal growth factor (EGFR) antagonist, erlotinib, which inhibits tyrosine kinase activity of EGFR." (PMID 18478076, 2008). "These new mouse models of mutant EGFR-dependent lung adenocarcinomas provide insight into clinical observations." (PMID 17726540, 2007). "Both transgenic lines develop lung adenocarcinomas that require mutant EGFR for tumor maintenance but are resistant to an EGFR kinase inhibitor." (PMID 17726540, 2007). "The prevalence of EGFR, BRAF, and PIK3CA mutations in lung adenocarcinomas was 6 (13/234), <1 (1/156), and 2% (2/132), respectively." (PMID 17487277, 2007). "Mouse models constructed to investigate the oncogenicity of mutant EGFR develop invasive lung adenocarcinomas that regress after treatment with EGFR TKIs." (PMID 18030354, 2007). "The status of K-Ras and EGFR has been previously determined in all of the cell lines used, except lung adenocarcinoma cell line UKY-29, isolated at the University of Kentucky." (PMID 17096850, 2006). "We identified lung adenocarcinoma cell lines sensitive to a representative EGFR TKI, erlotinib, by DNA content analysis using propidium iodide staining." (PMID 17096850, 2006). "Lung adenocarcinomas also harbor activating mutations in the downstream GTPase, KRAS, and mutations in EGFR and KRAS appear to be mutually exclusive." (PMID 15696205, 2005). "Somatic mutations in the tyrosine kinase domains of two ERBB genes, epidermal growth factor receptor (EGFR) and HER2, have been found in a proportion of lung adenocarcinomas." (PMID 15696205, 2005). "Immunocytochemical analysis revealed erbB-2 and EGFR coexperession as a characteristic feature of most lung adenocarcinomas, and at levels of receptor expression present in bronchial epithelial cells." (PMID 7599067, 1995). "The EGFR and KRAS genes are mutation hotspots in lung adenocarcinoma that occur randomly in MPLC." (PMID 41556052, 2026). "The purpose of this study was to identify the prognostic value of a combined assessment of serum markers in patients with lung adenocarcinoma and bone metastases undergoing EGFR-TKI treatment and to provide more accurate personalized treatment planning for clinical practices." (PMID 41551443, 2026). "Sortilin expression in lung adenocarcinoma may be predictive of the efficacy of anti-EGFR therapies." (PMID 41691060, 2026). "A comprehensive examination of serum markers may serve as a robust tool for predicting the outcomes of EGFR-TKI treatment in patients with lung adenocarcinoma and bone metastases." (PMID 41551443, 2026). "A 73-year-old woman with epidermal growth factor receptor (EGFR) L858R-mutant lung adenocarcinoma (cT4N1M1a stage IV, programmed death-ligand 1 (PD-L1) high expression (60%)) received osimertinib as first-line therapy, but disease progression was observed after two months." (PMID 41970061, 2026).
lung adenocarcinoma (continued). "Furthermore, coadministration of tamoxifen and the EGFR TKI gefitinib potentially inhibited p-EGFR expression in EGFR-mutant lung adenocarcinoma." (PMID 41597172, 2026). "Indeed, our de novo somatic indel calling from TCGA RNA-seq increases the TCGA driver indel repertoire by ∼14%, especially in samples with purity less than 0.4, including actionable EGFR indels in lung adenocarcinoma and FLT3 in acute myeloid leukemia." (PMID 41781335, 2026). "For those diagnosed with both ER-positive breast cancer and EGFR-mutant lung adenocarcinoma, combined tamoxifen and EGFR TKI therapy may offer an effective targeted treatment strategy." (PMID 41597172, 2026). "NGS testing identified a novel METex14 (c.2888-23_2888-8del) skipping mutation in the patient with advanced lung adenocarcinoma who developed resistance to EGFR-TKI, suggesting its potential involvement as one of the mechanisms underlying the resistance to EGFR-TKI." (PMID 40129940, 2025). "Similarly, heterogeneity parameters have been shown to predict epidermal growth factor receptor (EGFR) mutation status and treatment response in lung adenocarcinoma patients undergoing EGFR tyrosine kinase inhibitor therapy." (PMID 40717183, 2025). "A complete evaluation of the regulatory effects of ginsenoside Rg3 on the copy number of important EGFR exons and EGFR protein expression in lung adenocarcinoma cells from the perspectives of clinical efficacy, in vivo pharmacodynamic, and molecular biology was performed." (PMID 40732366, 2025). "The IMA had a much lower EGFR rate than typical lung adenocarcinoma." (PMID 40182027, 2025). "Common EGFR mutations (del exon 19 or exon 21 L858R) are associated with better overall survival (OS) compared to no-mutation lung adenocarcinoma." (PMID 40227775, 2025). "Furthermore, approximately half of the cases harbored EGFR mutations (3/7, 43%), suggesting that the double-positive cases for HNF4α and TTF-1 were derived from TRU-type lung adenocarcinomas." (PMID 38710944, 2025). "Our findings suggest that SII is associated with all-cause mortality in patients with stages IIIB–IV EGFR-mutated lung adenocarcinoma, regardless of mutation subtype, indicating the potential of SII as a prognostic blood biomarker." (PMID 41268168, 2025). "In addition, Daichi Fujimoto’s study has similarly described a significantly reduced frequency of EGFR mutations in patients with ILD and lung adenocarcinoma." (PMID 40507634, 2025). "Studies have shown that some patients with LCCA may harbor molecular mutations, including EGFR, KRAS, and ALK gene rearrangements, which are more commonly found in NSCLC, particularly in lung adenocarcinoma." (PMID 40927518, 2025). "The patient was diagnosed with EGFR‐mutant lung adenocarcinoma." (PMID 39727229, 2025). "Osimertinib resistance is the main challenge in treating EGFR-mutant lung adenocarcinoma (LUAD)." (PMID 41213916, 2025). "Furthermore, we discovered that early-stage EGFR-mutant lung adenocarcinoma patients with high TLS expression demonstrated longer disease-free survival (DFS) compared to those with low TLS expression." (PMID 40723259, 2025). "Epidermal growth factor receptor (EGFR) mutations are present in 66.3% of Asian non-smokers with lung adenocarcinoma (LUAD), and brain metastasis is detected in up to 29% of these patients at initial diagnosis." (PMID 40069781, 2025). "In addition, the miR-651-5p antagomir increased T cell infiltration and enhanced the efficacy of the PD-1 inhibitor treating the EGFR-mutant lung adenocarcinoma humanized mouse model." (PMID 40002895, 2025). "In EGFR-mutant lung adenocarcinomas, as in our case, fluorodeoxyglucose uptake on Positron emission tomography–CT may be deceptively low, and SUVmax values may not accurately reflect the true malignant potential." (PMID 41204513, 2025).
lung adenocarcinoma (continued). "In addition, EGFR TKI treatment can induce epigenetic reprogramming in EGFR-mutant lung adenocarcinoma (LUAD), facilitating its transformation into SCLC through a process that involves transitional cell states." (PMID 41220942, 2025). "Although the exact mechanism occurrence of prostate metastasis from lung adenocarcinoma remains unclear, possible explanations include vascular tropism through Batson’s plexus or interaction between EGFR and androgen receptor (AR) signaling pathways." (PMID 40740944, 2025). "Therefore, this study explored the expression and function of MCAM in EGFR-mutant the lung adenocarcinoma and the specific mechanism of EGFR-TKI resistance." (PMID 40713600, 2025). "However, the specific CAF subsets responsible for driving tumor advancement and resistance to EGFR‐TKIs in lung adenocarcinoma (LUAD) remain poorly understood." (PMID 40162549, 2025). "A similar trend was observed in stage IV lung adenocarcinoma patients treated with EGFR TKIs." (PMID 40361443, 2025). "In addition, it is worth noting that SCLC has the ability to transdifferentiate from lung adenocarcinoma (LUAD) when certain driver mutations, like epidermal growth factor receptor (EGFR), are lost." (PMID 39858036, 2025). "Common drivers in lung adenocarcinoma (but not lung squamous cell carcinoma) include EGFR and K-Ras mutations, which can serve as the activating signal upstream of STAT3." (PMID 41380973, 2025). "Furthermore, consistent with our findings, a previous study reported that ATG-10 can be used as a promising clinical predictor in advanced lung adenocarcinoma patients for gefitinib response which is an EGFR-TKI similar to Sorafenib." (PMID 39921803, 2025). "In a spontaneous lung adenocarcinoma generated by the expression of the EGFR L858R in type II pneumocytes under the control of doxycycline (Dox), induction of EGFR activated agrin expression within the multifocal adenocarcinomas when compared with adjacent or non‐induced lung tissues." (PMID 40165020, 2025). "It is possible that EGFR protein signaling may have a different prognostic role in the setting of advanced, unresectable lung adenocarcinoma in the dog, or that there were too few tumors that were EGFR negative in this study, resulting in a type II error." (PMID 40969344, 2025). "Tyrosine kinase inhibitors (TKIs) have substantially improved the management of lung adenocarcinoma harboring epidermal growth factor receptor (EGFR) mutations, however, not all patients can derive benefit from it." (PMID 40234395, 2025). "EGFR mutations occur in approximately 15-70% of all lung adenocarcinoma cases, with a higher prevalence in non-smokers, females and individuals of Asian origin." (PMID 40182027, 2025). "In addition, knockdown of 14-3-3ζ was shown to sensitize EGFR-TKI–resistant human lung adenocarcinoma cells to gefitinib and to inhibit EMT." (PMID 40316727, 2025). "Additionally, adenovirus expressing Cre‐recombinase that led to the expression of EGFR‐L858R/T790 M in mouse lungs formed spatially diffused lung adenocarcinoma with increased agrin expression." (PMID 40165020, 2025). "EGFR, the critical regulator of carcinogenesis in lung adenocarcinoma cells, may also be responsible for STAT3 phosphorylation in this context." (PMID 39985075, 2025). "Furthermore, we revealed the differentiated gene signatures and molecular functions between high- and low-TLS-density early-stage EGFR-mutant lung adenocarcinoma patients." (PMID 40723259, 2025). "Lung adenocarcinoma (LUAD), the most common subtype of non‐small‐cell lung cancer (NSCLC), is often driven by mutations, particularly in epidermal growth factor receptor (EGFR), that guide targeted therapy choices." (PMID 40720248, 2025). "In addition, we conducted IHC staining on 108 lung adenocarcinoma tissues and assessed the association between the protein levels of SHH, DUSP13B, p‐STAT3, and EGFR gene mutation status." (PMID 39721017, 2025).